LINC03124 (long independently transcribed non-coding RNA 3124)
Synonyms: C2orf27; C2orf27A; C2orf27B
Gene: Long non-coding RNA gene on chromosome 2 (131,647,982 to 131,774,655, forward strand). Ensembl gene ENSG00000287151.
Diseases named in the same sentence as LINC03124 in open-access papers:
LINC03124 is named in the same sentence as 1 disease in open-access papers, as found by Europe PMC text mining. Sharing a sentence is not in itself a finding about the gene and the disease.
LINC03124 shares sentences with these, for which no sentence is quoted: tumor (1 paper).